NMT1 (N-myristoyltransferase 1)
Diseases named in the same sentence as NMT1 in open-access papers (continued):
Sharing a sentence is not in itself a finding about the gene and the disease.
cancer (continued). "NMT1-mediated myristoylation leads to aberrant oncogene Src signalling, conferring cancer cells with greater aggressiveness and proliferative capacity, thereby promoting cancer development." (PMID 37140999, 2023). "Accumulating evidence has revealed that NMT1 is highly expressed in various cancers, and high expression of NMT1 is closely related to poor prognosis in cancer patients." (PMID 36617552, 2023). "Blocking NMT1-mediated myristoylation blocks both lysosomal catabolic and anabolic functions and means that targeting NMT1 is a promising anti-cancer strategy." (PMID 37140999, 2023). "First, the development of NMT inhibitors as anti-cancer therapeutics, which is the aim of this work, restricts the targets to human NMT1 and NMT2." (PMID 36080246, 2022). "Myristoyl-CoA analog B13 and its derivative LCL204 are inhibitors of NMT1 activity and Src myristoylation and compete for myristoyl-CoA binding sites, effectively inhibiting Src family kinase-mediated cancer." (PMID 36359005, 2022). "We also discovered an extra novel gene, N-myristoyltransferase 1 (Nmt1), after comparing our data with classical markers, which was previously reported to participate in the development of cancers." (PMID 34957241, 2021). "Accordingly, targeting the NMT1–LAMTOR1 axis using NMTi simultaneously inactivates mTORC1 and prevents lysosomal degradation, disrupting homeostasis and causing apoptosis in cancer cells." (PMID 32686708, 2020). "Analysis of CCLE NMT1 or NMT2 expression data reveals that in addition to be overexpressed in some cancers (aka the current dogma), NMT expression levels are actually lower in other cancers, many of which are of hematological origin." (PMID 33093447, 2020). "NMT1 sustains proliferation and/or survival of cancer cells through mechanisms that are not completely understood." (PMID 32686708, 2020). "In summary, we show that NMT1 is a novel regulator of lysosomal function in cancer cells, and that lysosomal degradation and mTORC1 activation can be simultaneously blocked by NMT inhibitors to limit tumor growth." (PMID 32686708, 2020). "In this study we report that NMT1 is an essential regulator of lysosomal metabolic functions in cancer cells." (PMID 32686708, 2020). "We used genetic and pharmacological inhibition of NMT1 to further dissect the role of this enzyme in cancer, and found an unexpected essential role for NMT1 at promoting lysosomal metabolic functions." (PMID 32686708, 2020). "Our findings uncover an additional function for NMT1 in cellular homeostasis, and a novel druggable lysosomal metabolic vulnerability of cancer cells." (PMID 32686708, 2020). "N-myristoyltransferase-1 (NMT1) catalyzes protein myristoylation, a lipid modification that is elevated in cancer cells." (PMID 32686708, 2020). "Although we still do not know why hematological cancer cells are more vulnerable to PCLX-001 than other cancer cell types, we think this is possibly related to altered expression of either NMT1 or NMT2." (PMID 33093447, 2020). "This indicated that NMT1 activity is necessary to maintain basal levels of mTORC1 activation in cancer cells." (PMID 32686708, 2020). "Here, we report an unexpected essential role for NMT1 in the regulation of lysosomal degradation and mTORC1 activation in cancer cells." (PMID 32686708, 2020). "Inhibition of NMT1 impaired lysosomal degradation and inhibited mTORC1, leading to decreased cancer cell proliferation, increased apoptosis and decreased tumor growth." (PMID 32686708, 2020). "This indicated that NMT1 is necessary for effective lysosomal degradation in cancer cells, in line with the observed delay in the autophagy flux, and the accumulation of p62SQSTM in cells treated with NMTi." (PMID 32686708, 2020). "It was found that the most significantly enriched pathway regulated by miRNAs that target both NMT1/2 genes and the MetAP2 gene was proteoglycans in cancer." (PMID 29579063, 2018).
cancer (continued). "These genes related to the selected probes are mostly associated with cancer and LN metastasis, such as TP73, PDX1, FUT8, HOXD1, NMT1, and SEMA3E." (PMID 28951630, 2017). "Inhibiting NMT1 activity resulted in reduced cancer progression in a murine model and increased apoptosis in different cancer cell lines." (PMID 27367672, 2016). "Increased NMT1 expression and activity is observed in multiple cancer types." (PMID 40748136, 2025). "Therefore, cancer cells low in NMT2 are likely to be low in NMT1 and possibly easier to eliminate pharmacologically because they have fewer enzymatic targets than normal cells." (PMID 38715059, 2024). "Interestingly, NMT1 dependency was significantly correlated with NMT2 expression in all cancer cell lines (r = 0.600; p < 0.0001)." (PMID 38715059, 2024). "Numerous studies indicate that while NMT1 is crucial for organismal growth and development, it is also an oncogenic protein that is aberrantly expressed in many human cancers, suggesting that NMT1-mediated protein myristoylation is a potential mechanism of tumorigenesis and development." (PMID 38485938, 2024). "It has been reported that myristoylation mediated by NMT1 results in abnormal oncogene Src signaling, which enhances the aggressiveness and proliferative ability of cancer cells, thereby contributing to the progression of cancer." (PMID 38338729, 2024). "NMT1 expression and activity are altered in various types of cancer tissues." (PMID 37140999, 2023). "Growing evidence suggests that NMT1 regulates cancer cell metabolism." (PMID 37140999, 2023). "Thus, in the unlikely event that some of the identified hits display selectivity against NMT1, the findings will remain relevant to the goal of development of therapeutics with anti-cancer activity." (PMID 36080246, 2022). "NMT1 is necessary for lysosomal degradation and mTORC1 activation in cancer cells." (PMID 34095144, 2021). "However, based on our experiments we cannot completely rule-out that additional NMT1 targets contribute to lysosomal metabolic functions in cancer cells." (PMID 32686708, 2020). "Our findings suggest that compounds targeting NMT1 may have therapeutic benefit in cancer by preventing mTORC1 activation and simultaneously blocking lysosomal degradation, leading to cancer cell death." (PMID 32686708, 2020). "While we still do not know why hematological cancer cells are more vulnerable to PCLX-001 than other cancer cell types, we think this might be related to alterations in NMT1 or NMT2 expression in hematological cancer cells." (PMID 33093447, 2020). "We show that NMT1 is required for both lysosomal functions in cancer cells." (PMID 32686708, 2020). "However, there are few studies have specifically examined the role of prolonged inhibition of NMT1 on cancer." (PMID 30446635, 2018). "NMT1 is necessary for lysosomal degradation and mTORC1 activation in cancer cells, and compounds targeting NMT1 may have therapeutic benefit in cancer by preventing mTORC1 activation and simultaneously blocking lysosomal degradation, leading to cancer cell death." (PMID 36967718, 2023). "The accurate identification of NMT1 and NMT2 protein levels may be of particular importance in cancer since numerous cancer types were previously demonstrated to exhibit variabilities in NMT expression/protein levels and because of this may be targeted with NMT-directed therapeutics." (PMID 33398478, 2021). "Our findings are in agreement with previous reports indicating that NMT1 is a cancer therapeutic target, and support a general homeostatic function of NMT1 in cancer that is beyond oncoprotein myristoylation, and which could be exploited for therapeutic purposes in different cancer types." (PMID 32686708, 2020).
cancer (continued). "Whereas we cannot completely rule out a role for NMT2 in lysosomal metabolism, we observed that silencing of NMT1 was sufficient to recapitulate the effects of NMTi treatment, indicating that NMT1 is likely the main enzyme involved in regulating lysosomal functions in cancer cells." (PMID 32686708, 2020). "The NMT1 inhibitor low-dose PCLX-001 blocks CHP1 myristoylation, disrupting excessive PD-L1 membrane localization and attenuating cancer immune suppression." (PMID 40605065, 2025). "Based on the results of pan-cancer analysis, we found that GLRX2, NMT1, PPP2R2B and TRAF3IP3 exhibited a dysregulated level in many types of tumors, highlighting their potential roles in tumor progression." (PMID 38409085, 2024). "A number of cell membrane proteins such as N-myristoyltransferase 1 (NMT 1), CD71, Ep-CAM and MIF are seen to be extracted by MGL differentially from C1GalT1-expressing and knockdown cancer cells in this study." (PMID 37612278, 2023). "Although many studies propose Tris DBA as a modulator of MAPK, Akt, phospho-S6 kinase, and N-myristoyltransferase-1, we have comprehensively demonstrated for the first time that Tris DBA is an inhibitor of STAT3 signaling in preclinical cancer models." (PMID 34771643, 2021). "The specific mechanism by which NMT1 and LAMTOR1 promote lysosomal degradation in cancer cells remains to be determined." (PMID 32686708, 2020). "The association of microRNAs (miRNAs) that target N-myristoyltransferase (NMT) transcript 1 and 2 (NMT1 and NMT2) with different cancer types and their expression changes." (PMID 29579063, 2018). "The feature selection procedure extracted several cancer-related and lymph node metastasis-related genes, such as TP73, PDX1, FUT8, HOXD1, NMT1, and SEMA3E." (PMID 28951630, 2017). "CRISPR/Cas9 KOs in 1078 cancer cell lines revealed that while NMT2 (average gene effect score = 0.171 ± 0.003) is a non-essential gene, NMT1 can be characterized as an essential gene in cancer cells with an average gene effect score of 0.855 ± 0.015." (PMID 38715059, 2024). "Interestingly, cancer cells that were low in NMT2, highly dependent on NMT1, or predicted to be sensitive to NMTI treatment (high MISS-54 score) showed high MYC expression." (PMID 38715059, 2024). "However, the exact mechanism by which NMT1 and LAMTOR1 promote lysosomal degradation in cancer cells remains to be determined." (PMID 37140999, 2023). "Our findings indicate the effectiveness of NMT1 inhibition at blocking lysosomal metabolic functions in vivo, and suggest that the NMT inhibitor DDD85646 represents a novel class of lysosomal targeting agent with promising therapeutic value in cancer." (PMID 32686708, 2020). "But the mechanisms of targeting NMT1 to suppress cancer progression were not clearly illustrated yet." (PMID 30446635, 2018). "Recent findings suggest that N-myristoylation, particularly through the upregulation of N-myristoyltransferase 1 (NMT1) in hypoxic tumor environments, could play a pivotal role in cancer progression, given its involvement in cell proliferation, the cell cycle, and death pathways." (PMID 40605065, 2025). "For combination strategies, exploring the synergistic effects of NMT1 inhibitors with oncolytic viruses or CAR-T-cell therapy could be promising, with the aim of further activating antitumor immune responses and broadening the treatment landscape for cancer." (PMID 40605065, 2025). "PCLX- 001 (Zelenirstat), the first pan-NMT inhibitor tested in humans, targeting NMT1 and NMT2, interferes with Src family kinases and energy metabolism by promoting the degradation of NDUFAF4, an essential assembly factor for respiratory complex I in cancer cells." (PMID 40335986, 2025). "However, few oncoproteins are myristoylated; thus, the mechanisms by which NMT1 contributes to cancer progression in most tumors are not well defined." (PMID 38949950, 2024).
cancer (continued). "Collectively, these findings indicate that sustained NMT1 activity is necessary for LAMTOR1-dependent lysosomal localization of mTORC1, and that lysosomal mTORC1 localization and activation can be effectively disrupted with a small molecule inhibitor of NMT in cancer cells." (PMID 32686708, 2020). "Expression of NMT1 is relatively constant across the 1269 cell lines investigated with a slight but significant decrease in expression in breast and leukemia cancer cell lines while NMT2 expression varies significantly amongst various cancers and also within a given cancer type." (PMID 33093447, 2020). "Our finding that TFE3 further accumulates in the nucleus of cancer cells lacking NMT1, LAMTOR1, or in cells treated with NMTi is consistent with both the inhibition of mTORC1 activity by NMTi, and the autophagy blockade provoked by the lack of degradative lysosomal activity." (PMID 32686708, 2020).
tumor (28 papers, 2011 to 2025). "We observed a strong association between high NMT1 and Src expression, more aggressive tumours, increased recurrence risk and decreased DFS in PTC." (PMID 40748136, 2025). "Staining analysis of phenotypic molecules related to the tumor immune microenvironment revealed that high NMT1 expression was associated with reduced CD8+ T-cell infiltration." (PMID 40605065, 2025). "To investigate the specific mechanisms by which NMT1 regulates tumor progression and prognosis, we first analyzed the effects of NMT1 expression loss on the biological behavior of tumor cells via in vitro functional assays." (PMID 40605065, 2025). "Systematic analysis of data from the TCGA database further revealed that NMT1 expression is closely associated with tumor immune evasion." (PMID 40605065, 2025). "Due to the loss of NMT2 expression in certain tumor types, there is a growing interest in developing selective inhibitors for NMT1." (PMID 37511367, 2023). "In this review, we discuss the underlying mechanisms by which NMT1 is associated with tumour development from the perspective of oncogene signalling, involvement in cellular metabolism, and endoplasmic reticulum stress." (PMID 37140999, 2023). "Elevated NMT1 expression could be linked to interactions involving the extracellular matrix and neuroactive ligand receptor pathways, implying a potential involvement of NMT1 in tumor cell interactions with the extracellular matrix and neuro-pathways." (PMID 38654047, 2024). "Furthermore, an elevated level of NMT1 in tumours is associated with poor survival." (PMID 37140999, 2023). "In addition, poor survival outcomes of tumours are associated with NMT1 levels in the tumours." (PMID 37140999, 2023). "Since knocking out NMT1 leads to the death of tumor cells, we designed three shRNAs (shNMT1-658, shNMT1-557, and shNMT1-267) that target the NMT1 gene and constructed lentiviral vectors." (PMID 40605065, 2025). "Immunofluorescence staining of tumor sections revealed a positive correlation between NMT1 and HIF1α expression (r = 0.8213, p < 0.0001)." (PMID 40605065, 2025). "Knockdown or overexpression of NMT1 confirmed that its expression directly regulates N-myristoylation levels in tumor cells." (PMID 40605065, 2025). "Immunohistochemical analysis of tumor tissues revealed that the expression level of NMT1 was greater than that in adjacent normal tissues (p = 0.0439)." (PMID 40605065, 2025). "To validate the role of NMT1 in clinical samples, we analyzed tumor tissues and prognostic data from patients with HNSCC." (PMID 40605065, 2025). "Upregulation of NMT1 expression enhanced but NMT1 knockdown suppressed tumor growth in vitro and in vivo." (PMID 36617552, 2023). "More importantly, we found that the expression of VILIP3 was positively correlated with NMT1 level in tumor tissues." (PMID 36617552, 2023). "This review provides an overview of recent advances concerning the relationship between NMT1 and various tumours, thus highlighting the unique role of NMT1 in tumours and providing suggestions for future research areas." (PMID 37140999, 2023). "In summary, this research identified NMT1 as a tumor promoter in GC and revealed that SPI1 mediated NMT1 to facilitate GC cell viability, migration, and invasion by activating the PI3K/AKT/mTOR pathway." (PMID 36967718, 2023). "Tris DBA was initially described as an inhibitor of N-myristoyltransferase-1 and here we have comprehensively demonstrated its mode-of-action in two different tumor models." (PMID 34771643, 2021). "Further, knocking NMT1 down significantly impaired transformative phenotypes including reduced cell proliferation, colony formation, and in vivo tumor growth capacities whereas induced caspase 3/7 activity." (PMID 34136404, 2021). "Pharmacological inhibition of NMT1 reduced tumor growth, and tumors from treated animals had increased apoptosis and displayed markers of lysosomal dysfunction." (PMID 32686708, 2020).